IL6 (interleukin 6)
Diseases named in the same sentence as IL6 in open-access papers (continued):
Sharing a sentence is not in itself a finding about the gene and the disease.
COVID-19 (continued). "After completing plitidepsin treatment, 15.5% (7 of 45) of patients received other additional treatments for COVID-19, including the anti-viral agent remdesivir (one patient) and/or the anti-IL-6 monoclonal antibody tocilizumab (six patients)." (PMID 35012962, 2022). "Our model shows that, in a situation with rapid, high, dysregulated IL-6 production – such as severe COVID-19 or a cytokine storm – an initial dose of either an anti-IL-6 or anti-IL-6R mAb inhibits IL-6 bioactivity." (PMID 35928820, 2022). "Only one observational study compared IL-1 and IL-6 inhibition in COVID-19 patients and found that anakinra was more effective." (PMID 36209522, 2022). "The increased IL-6 levels in response to COVID-19 and acidosis also result in ferritin production, leading to intracellular iron accumulation, which damages the tissue." (PMID 35806905, 2022). "We have reported the application of a cytokine panel (serum, IL-1β, IL-6, IL-8 and TNFα) using the automated EllaTM platform and its potential clinical utility in the assessment of patients with COVID-19." (PMID 35500008, 2022). "Inflammation, hypoxia, reduced levels of angiotensin converting enzyme 2, elevated levels of Interleukin 6 and some other cytokines that are hallmarks of COVID-19 are capable of inducing tumor relapse and metastasis." (PMID 36404512, 2022). "Patients with severe COVID-19 have considerable IL-6 overexpression, and IL-6 signal transduction is the most upregulated pathway in COVID-19 patients." (PMID 35784318, 2022). "The current study observed hyperregulation of IL-1 and IL-6 among COVID-19 infected individuals as observed previously." (PMID 36298704, 2022). "In our study, patients with the severe form of acute COVID-19 had higher levels of IL-6 and had some type of comorbidity (diabetes mellitus, hypertension, obesity, and immunosuppression)." (PMID 35846757, 2022). "In patients with severe COVID-19, a strong activation of alveolar macrophages and very high pulmonary concentrations of proinflammatory mediators (IL-6, IL-8, IL-1β) and chemokines were found." (PMID 35457086, 2022). "A key player in this cytokine response is IL-6, circulating levels of which are significantly elevated in COVID-19 patients, and as such its presence has been reported to contribute to the vascular pathology." (PMID 35318338, 2022). "IL-6 has been known to drive CRP production primarily in the liver and as a driver of the COVID-19 cytokine storm associated with poor COVID-19 outcomes." (PMID 35510030, 2022). "Recent studies described strong associations between metabolites, including the kynurenine pathway of tryptophan metabolism and proinflammatory cytokines/chemokines (e.g., interleukin (IL)-1 and IL-6) in COVID-19 patients." (PMID 36290606, 2022). "Patients with severe COVID-19 reportedly have high levels of proinflammatory cytokines such as IL-2R, IL-6, and TNF-α." (PMID 36246680, 2022). "Serum DPP4 activity significantly correlated with clinically meaningful parameters in COVID-19, including the patients' ages, absolute lymphocyte count and serum albumin, C-reactive protein, IL-6 and plasma D-dimer levels." (PMID 35195023, 2022). "Monoclonal antibodies targeting IL-6 such as tocilizumab are licensed for use in autoimmune diseases and have been shown to be useful in COVID-19 with defined and acceptable side-effect profiles." (PMID 35790656, 2022). "Comparative analysis of COVID-19 patients according to Discharge or Death outcome demonstrated that the latter presented higher IL-6 and CXCL10 levels at corresponding timepoints." (PMID 36451835, 2022). "The oversecretion of proinflammatory cytokines such as IL-6, IL-8, and TNF-α during COVID-19 causes pulmonary dysfunction, which exacerbates clinical symptoms and is improved by suppressing the immune system." (PMID 36531832, 2022).
COVID-19 (continued). "IL-6 expression significantly increased in patients with critical COVID-19, and the protective GG genotype of IL-6 rs2069837 decreased the expression of IL-6 in the serum compared to its expression using the AA genotype." (PMID 35368020, 2022). "Post hoc analysis with Mann–Whitney U test post hoc analysis showed that IL-6 blood concentration differences were significantly different across all COVID-19 severity subgroups analyzed." (PMID 33983525, 2022). "Immune cells in COVID-19 patients produce inflammatory cytokines such as IL-2 and IL-6 to stimulate B-cell proliferation." (PMID 35185890, 2022). "ROC curves for plasma levels of GABA below 0.214 μmol/L allowed for discrimination of COVID-19 patients with good sensitivity and specificity (AUC = 93%) significantly exceeding the predictive power of IL-6 (AUC = 78%, Suppl." (PMID 35064792, 2022). "Similar to dengue, those who proceed to develop severe COVID-19 have high levels of many proinflammatory cytokines such as IL-6, IL-1β, IL-10, CXCL-10, MCP-1 and the cytokine storm is shown to associate with both severe dengue and COVID-19." (PMID 35786403, 2022). "It was a retrospective study, and some relevant data, such as smoking history, as well as some test results, such as IL-6, which is a known prognostic factor for COVID-19, were incomplete." (PMID 35989853, 2022). "Noteworthy, among all the elevated inflammatory mediators, the blood IL-6 level is highly correlated with disease mortality, which suggests that fatal COVID-19 is characterized by a cytokine release syndrome (CRS) induced by a cytokine storm." (PMID 34802072, 2022). "The REMAP-CAP trial experimented with the use of tocilizumab and another IL-6 inhibitor (sarilimumab) in critically ill COVID-19 patients: patients treated with both drugs showed better outcomes, including survival, compared to standard care." (PMID 35208467, 2022). "In this study, we systematically analyzed the serum levels of IL-1β, IL-2, IL-4, IL-6, IL-8, and IL-10 in COVID-19 patients with different disease severities, as well as in healthy controls." (PMID 35540724, 2022). "Plasma levels of TNFα, IL-2, IL-6, IL-8, IL-10 (p < 0.001), IFNγ (p < 0.01), and GM-CSF (p < 0.05) were higher in COVID-19 patients compared to in HCs." (PMID 35625671, 2022). "Drawing on an available biobank of samples from 35 patients hospitalized with COVID-19, a novel quantum-magnetic sensing platform is used to determine plasma IL-6 concentrations." (PMID 35626318, 2022). "High levels of IL-6 production were recorded and reliant on the inflammatory monocytes’ activation as the distinct functions of Th1 cells in the severe form of COVID-19." (PMID 35566589, 2022). "The elevation of the IL-6 marker is correlated with a maladaptive immune response in COVID-19 patients, leading to worse outcomes and higher mortality." (PMID 35274050, 2022). "We observed that IL-6 expression in lung tissue belonging to COVID-19 patients was comparable to what was observed in control subjects." (PMID 36422642, 2022). "Interleukin-6 (IL-6) receptor antagonists exhibit anti-inflammatory effects by reducing the elevation of IL-6, and IL-6 is an important mediator for severe systemic inflammatory responses in patients with COVID-19." (PMID 35721224, 2022). "In this research, we detected a significant content of IL-1β and IL-6 in the saliva of the V-COVID-19 group at the moment of the PCR diagnosis." (PMID 36497139, 2022). "Severe COVID-19 courses are characterized by hyperinflammation and cytokine storms, with significantly higher serum levels of interleukin (IL)-6, IL-8, IL-10, IL-2R and tumor necrosis factor (TNF)-alpha." (PMID 34608263, 2022). "Monoclonal antibodies targeting IL-6 and IL-6 receptors are recommended by Italian and American guidelines to treat patients with severe and critical COVID-19." (PMID 35645219, 2022).
COVID-19 (continued). "For instance, among the spectrum of cytokines elevated in critically ill COVID-19 patients, IL-6 is a pleiotropic molecule regulating a significant number of genes and having a dual role in antiviral cellular responses." (PMID 35647937, 2022). "It was considered as a potential COVID-19 treatment due to the ability of the virus to induce the production of various cytokines such as IL-1β, IL-6, tumor necrosis factor, and others." (PMID 34802072, 2022). "A study is reported that an exacerbated inflammatory response in severe COVID-19 patients associated with increased TNF-a and IL-6 potentially driven by NF-κB." (PMID 35223745, 2022). "Further analysis revealed that there was a significantly stronger expression of IL-6 in the serum from patients with critical COVID-19 than in that from patients with asymptomatic COVID-19." (PMID 35368020, 2022). "In a recent study, morning salivary cortisol was similar between the control group and patients with COVID-19, and evening and nighttime cortisol levels were high and correlated with IL-6 levels." (PMID 36016249, 2022). "CYP1A2 showed a decrease of 53% during SARS-CoV-2 infection measured in blood samples from 18 COVID-19 patients, with an inverse correlation with interleukin 6 and C-reactive protein levels." (PMID 36052135, 2022). "Elevated pro-inflammatory cytokine is a typical profile in patients with COVID-19, such as IL-6, IL-1, and tumor necrosis factor (TNF)-α." (PMID 35957855, 2022). "In the COVID-19 patients’ cells, IL-6 and other peripheral blood inflammatory factors are elevated, and the expression level of IL-6 is positively correlated with the severity of COVID-19." (PMID 35573742, 2022). "The levels of antiviral antibodies targeting NSP10 were negatively correlated with systemic levels of IL-6 in COVID-19 patients." (PMID 35582921, 2022). "Anti-inflammatory therapies used in COVID-19 include the corticosteroid Dexamethasone and IL-6 inhibitor Tocilizumab." (PMID 35901224, 2022). "A significant role in the COVID-19 cytokine storm is played by the inflammatory cytokine IL-6, acting as a major player in the systemic effect of pro-inflammatory acute inflammatory response." (PMID 35740951, 2022). "Our findings demonstrated that two groups of COVID-19 patients had significant increases in four pro-inflammatory cytokines (IL-1β, IL-6, and IL-18) and two anti-inflammatory cytokines (IL-4 and IL-35)." (PMID 36298501, 2022). "The results of a meta-analysis reviewing six studies showed that interleukin-6 levels were significantly increased (2.9-fold) in severe COVID-19 cases compared to mild cases." (PMID 35281265, 2022). "The key perpetrating pro-inflammatory cytokines which were targeted to manage the symptoms of COVID-19 are IL6 and TNF-α." (PMID 36386162, 2022). "The QDTI platform has the potential to serve as a point-of-care test for the accurate detection of IL-6 concentrations for patients with COVID-19 as well as other IL-6 mediated diseases." (PMID 35626318, 2022). "These patients—57% of the cohort—had high IL-6 levels up to three months after being infected with COVID-19." (PMID 35624943, 2022). "Upon activation, caspase 1 processes pro-IL-1β and pro-ΙL-18 into their functional cytokine forms, which initiate the production of several other cytokines such as IL-6, IL-8, and TNFα, all of them overexpressed in severe COVID-19." (PMID 36498845, 2022). "It has been shown that both in MAS and HLH, but especially in severe COVID-19, it is implicated the dysfunction of type I interferon, NK cells, with extensive CTL involvement, increased IL-6, TNF-α, and excessive inflammation caused by the NF-kB pathway." (PMID 35457086, 2022). "In conclusion, the major cytokines in COVID-19 pathophysiology, including IL-6, IL-8, and TNF-α, are significantly improved by Photobiomodulation, as is the IL-6/IL-10 ratio." (PMID 35874678, 2022).
COVID-19 (continued). "Even though these are preliminary data from a carcinoma cell line, infection-induced apoptosis and triggered inflammatory response with enhanced expression of IL-6, which is elevated in COVID-19 patients and correlates with adverse clinical outcome." (PMID 35332140, 2022). "A study that analyzed the levels of 11 cytokines among COVID-19 patients found that the highest IL-6 levels coincide with disease severity, suggesting a strong link between this inflammatory cytokine and the pathogenesis of severe COVID-19." (PMID 36295550, 2022). "This study attempts to explore and evaluate the correlation between the severity of COVID-19 and different contributors such as testosterone and inhibin B as sex-related parameters and the inflammatory mediators; IL-6 and TNF-a among Jordanian males." (PMID 36381078, 2022). "IL-6 has been considered the main and most relevant parameter in predicting the most severe course of respiratory failure, lung injury, and death in COVID-19." (PMID 35739949, 2022). "As for IL-6, the reported data suggest an increased expression in COVID-19 patients, a finding that differs from what we described." (PMID 36422642, 2022). "Anemia was the strongest predictor in association with COVID-19 (β = 3.65, CI = 1.46–5.39, p-value < 0.001), followed by elevated CRP (β = 2.11, CI = 1.20–3.06, p-value < 0.001), and respectively IL-6 (β = 1.92, CI = 1.20–2.47, p-value = 0.001)." (PMID 36579593, 2022). "In fact, apart from the well-known cytokine storm, COVID-19 patients with inflammatory neurological disease or encephalopathy, had specific increase in circulating IL-6, IL-8 and TGF-β1." (PMID 35982454, 2022). "COVID-19 plasma exosomes from patients later in their hospitalization induced the production of IL-6, TGFβ, and IL-10 compared with plasma exosomes from early-stage patients or non-COVID donors in Tregs." (PMID 36526691, 2022). "Patients with COVID-19 have shown deteriorating lung function is almost exclusively related to the inflammatory cytokine IL-6." (PMID 36298446, 2022). "IL-6 levels in samples derived from patients with severe COVID-19 course of disease were higher than from patients with mild symptoms (C19 mild: 34.3 ± 7.9 ng/L, C19 severe: 128.3 ± 51.5 ng/L, healthy reference: 7 ng/μL)." (PMID 35867189, 2022). "There is an association between plasma levels of IL-6 and the development of AKI in patients with COVID-19." (PMID 36430671, 2022). "The expression levels of hsa_circ_0000479, RIG-I, and IL-6 were increased in COVID-19 patients compared to healthy controls, while hsa-miR-149-5p expression was decreased." (PMID 36081604, 2022). "Procoagulant changes and abnormal coagulation tests are seen in COVID-19 and SLE patients, which can be associated with the role of IL-6 in increasing fibrinogen levels." (PMID 35495619, 2022). "Results concerning interleukin-6 inhibitors, particularly tocilizumab, spark interest in a potential role of tocilizumab in select cases of severe COVID-19 with elevated levels of inflammatory markers." (PMID 35215217, 2022). "In order to get further insight into the value of IL-6 signalling variables in the prediction of death in COVID-19, new analyses were performed focused on severe patients (survivors and non-survivors)." (PMID 35634332, 2022). "In the COVID-19 cohort, IL6, PTSG2, JUN, ATF3, SOCS3, CSF3, and NFKB2 had AUC values greater than 0.7." (PMID 36380355, 2022). "In all carriers of genotypes ACE1 rs1799752 and ACE2 rs1978124, the amount of IL-6 was noticeably increased in the control group compared with the COVID-19 group, as well as outpatients compared with inpatients, and in the survived compared with the expired." (PMID 36134024, 2022). "When compared with the non-severe (asymptomatic, mild, or moderate) presentations, the patients with severe COVID-19 had significantly higher body mass index (BMI), higher serum concentrations of ferritin, lower lymphocyte counts, but similar IL-6 levels." (PMID 36289725, 2022).
COVID-19 (continued). "The ROC curves assembled highlighted that PDGF, IFN-γ and IL-6 presented substantial global accuracy to categorize COVID-19 and HC patients." (PMID 36451835, 2022). "The upregulation of IL-6, in particular, has been correlated with poor COVID-19 prognosis in a large study of 1,473 patients." (PMID 35955740, 2022). "In the present study, we found that increased CRP, IL-6, KL-6, HMGB-1, and d-dimer levels and decreased platelet counts early after admission were associated with the start of MV due to COVID-19." (PMID 35204430, 2022). "Cytokine inhibitors, like the IL-1 antagonist Anakinra or the IL-6 antagonist Tocilizumab, were used for immuno-rheumatological pathologies, and their use in COVID-19 patients requires validation." (PMID 35629072, 2022). "Immune system dysfunction and IL6 overexpression are characteristics of COVID-19, and elevated IL6 levels are related to respiratory failure and death." (PMID 35165525, 2022). "Many cytokines have been reported to be increased in severe COVID-19 patients and a few of them, such as IL-6, IL-8, IL-10 and TNF-α, are considered to be indicators of severe disease." (PMID 35337002, 2022). "A similar pattern of upregulated proteins, especially chemokines such as CXCL10, and cytokines such as IL-6, is seen in the airways during acute COVID-19." (PMID 35151371, 2022). "The main pathologic feature of severe COVID-19 is an excessive inflammation with a central role of interleukin (IL)-6, which is consistently upregulated." (PMID 35883726, 2022). "Data have shown that IL-6 levels are also significantly higher in COVID-19 patients with severe disease compared with those with a non-severe condition." (PMID 35678023, 2022). "Specialized pro-resolving mediators have been found to reduce the production of pro-inflammatory cytokines such as IL-6 and IL-1β, which are involved in the development of COVID-19." (PMID 36233111, 2022). "pGSN/IL-6 was the strongest predictive marker (amongst other cytokines) for mild COVID-19+ cases, ICU admissions and patient discharge." (PMID 36148234, 2022). "Herein, we aimed to evaluate the changes in serum IL-6, IL-10, and IL-17A levels and cytometric lymphocyte profiles in 144 COVID-19 patients at admission and after one week, also in relation to steroid treatment before hospitalization." (PMID 35893398, 2022). "Elevated IL-6 levels were reported in severely affected COVID-19 patients and correlated with high mortality." (PMID 35058480, 2022). "The results showed that the level of pro-inflammatory cytokines, TNF-α, IL-6, IL-8, and IL-1β were significantly elevated in severe COVID-19 patients, but the alarmin molecules IL-1α and HMGB1 were marginally higher." (PMID 36585712, 2022). "IL-6 is also reported as one of the good predictors of progression and severity in patients with COVID-19." (PMID 35493729, 2022). "In the lungs of COVID-19 patients, IL-6 can be released by SARS-CoV-2 infected respiratory epithelial cells, as well as by infiltrating CD14+CD16+ monocytes-macrophages and CD4+ T cells." (PMID 35340805, 2022). "In severe COVID-19, the major cytokines generated as part of immune response are IL-1β, IL-2, IL-6, and TNF." (PMID 35281470, 2022). "Systemic and lung IL-6 levels progressively increase in COVID-19 patients with disease severity, reaching the peak in the critical ones, the results being typically associated with lymphopenia, systemic inflammation, hypoxemia, and unfavorable prognosis." (PMID 35645219, 2022). "For instance, in severe COVID-19 patients, high-dose administration of ascorbate resulted in lower IL-6 levels compared to a placebo group." (PMID 36009299, 2022). "In the next stage of the study, we measured the IL-6 serum of the patients with critical COVID-19 and compared it to that of asymptomatic patients." (PMID 35368020, 2022).